ANKEF1 (ankyrin repeat and EF-hand domain containing 1)
Synonyms: ANKRD5; FLJ21669; dJ839B4.6
Tractability: Antibody: the Human Protein Atlas places it where antibodies can reach. PROTAC: ubiquitination databases record sites on it.
Gene: Protein-coding gene on chromosome 20 (9,986,126 to 10,058,303, forward strand). Ensembl gene ENSG00000132623.
Subcellular location (Human Protein Atlas): Cytosol; Nucleoli fibrillar center; Plasma membrane
Gene Ontology:
Molecular function: protein binding; calcium ion binding
Genetic constraint (gnomAD): Loss-of-function variants: 34 observed, 58.78 expected, observed/expected ratio (o/e) 0.58, 90% interval 0.44 to 0.77. The upper end of that interval is the gene's LOEUF score, 0.77, which puts it in group 3 of 6, group 1 being the genes least tolerant of losing a copy. Missense variants: 855 observed, 922 expected, observed/expected ratio (o/e) 0.93, 90% interval 0.88 to 0.98. Synonymous variants: 297 observed, 331.5 expected, observed/expected ratio (o/e) 0.9, 90% interval 0.81 to 0.99.
Homologues: Orthologues: chimpanzee ANKEF1 (99% identical), macaque ANKEF1 (96% identical), rabbit ANKEF1 (89% identical), dog ANKEF1 (87% identical), pig ANKEF1 (87% identical), mouse Ankef1 (85% identical), guinea pig ANKEF1 (85% identical), rat Ankef1 (85% identical), tropical clawed frog ankef1 (57% identical), zebrafish ankef1a (49% identical), zebrafish ankef1b (40% identical).
Diseases named in the same sentence as ANKEF1 in open-access papers:
ANKEF1 is named in the same sentence as 6 diseases in open-access papers, as found by Europe PMC text mining. Sharing a sentence is not in itself a finding about the gene and the disease. The quoted sentences say what the papers report.
coloboma (1 paper, 2023). An abnormality in which a part of a structure in one or both eyes is missing. "Mouse Ankef1 lies within the coloboma (Cm) deletion locus, whose phenotypes include auditory and vestibular deficits." (PMID 37367482, 2023). "Mouse Ankef1 is within the coloboma (Cm) deletion locus, the phenotypes of which include planar polarity defects in the cochlear epithelium, supernumerary hair cells, and hearing and balance defects." (PMID 37367482, 2023). "However, the mouse Ankef1 ortholog is located within the coloboma (Cm) deletion locus." (PMID 37367482, 2023).
deafness (1 paper, 2023). An inherited or acquired condition characterized by the complete loss of the ability to hear from one or both ears. "Human ANKEF1, ODF3L2, and SAXO2 chromosomal locations compared to potentially associated deafness loci." (PMID 37367482, 2023). "Human ANKEF1 is on chromosome 20 (GRCh38: 20:10034987-10058303) and is not located near any known human deafness loci." (PMID 37367482, 2023).
Infertility (1 paper, 2025). "To determine the cause of infertility in Ankef1 knockout mice, we performed IVF assays." (PMID 41460250, 2025). "Male Ankef1−/− mice exhibited impaired sperm motility and infertility." (PMID 41460250, 2025).
male infertility (1 paper, 2025). The inability of the male to effect fertilization of an ovum after a specified period of unprotected intercourse. "However, Ankef1-deficient mice did not display abnormalities in viability or general locomotor function beyond male infertility, suggesting that ANKEF1 may exert a tissue-specific role, with essential function limited to the male reproductive system." (PMID 41460250, 2025). "Fertility testing revealed that Ankef1–/– males were capable of mating with wild-type females but failed to produce offspring, indicating complete male infertility." (PMID 41460250, 2025). "Absence of ANKEF1 results in diminished sperm motility and consequent male infertility." (PMID 41460250, 2025).
ANKEF1 also shares sentences with these, for which no sentence is quoted: breast carcinoma (1 paper); cancer (1).